INS (insulin)
Diseases named in the same sentence as INS in open-access papers (continued):
Sharing a sentence is not in itself a finding about the gene and the disease.
Insulin resistance (continued). "In insulin-resistant HepG2 cells, enhancing the activities of HK and PK may significantly improve glucose uptake, offering a promising strategy to counteract insulin resistance." (PMID 38472847, 2024). "In patients with chronic heart failure, the combined application of an ACE1 inhibitor (enalapril) and losartan for 16 weeks significantly reduced plasma insulin levels, homeostatic model assessment of insulin resistance (HOMA-IR), TNF-α, interleukin-6, and MCP-1 levels." (PMID 38279313, 2024). "Insulin resistance is a consequence of various cellular pathway disruptions, leading to a reduced responsiveness of peripheral tissue cells, especially those in the muscle, liver, and adipose tissue, to insulin." (PMID 38611884, 2024). "Some researchers have suggested that following exposure to a high-fat diet (HFD), mice with 10% NEU1 activity in their tissues develop glucose intolerance and insulin resistance faster than wild-type mice, and suffer other repercussions such as impaired insulin signaling in their tissues." (PMID 39194692, 2024). "The review revealed marked improvements in insulin levels, yet no significant changes were noted in glucose, triglycerides, and adipose tissue hormones, which are typically linked to insulin resistance." (PMID 39339666, 2024). "Insulin resistance reduces the inhibitory effect of insulin on glucose formation and lipolysis." (PMID 39376658, 2024). "Another hypothesis is that resistin acts as an insulin antagonist, and thus, insulin resistance might suppress resistin levels, but further research is necessary to elucidate the precise role of resistin in these metabolic alterations." (PMID 38892541, 2024). "Insulin resistance (IR), which is defined as reduced or impaired insulin sensitivity in insulin-dependent tissues or organs shown by impaired glucose uptake and oxidation, is a significant risk factor for the development of type 2 diabetes and coronary artery disease." (PMID 38200157, 2024). "ISSI-2 is in general considered to be a more accurate marker of β-cell function in women with GDM as it reflects an insulin resistance-adjusted insulin secretion (analogous to the disposition index obtained from the frequently sampled intravenous glucose tolerance test)." (PMID 38933819, 2024). "Studies have shown that overexpression of GLUT4 could improve insulin resistance and insulin action in diabetic mice, indicating that GLUT4 translocation plays a crucial role in whole-body glucose homeostasis." (PMID 39749015, 2024). "Addressing insulin resistance in skeletal muscle can restore whole-body glucose homeostasis, making the promotion of glucose uptake and insulin sensitivity in skeletal muscles crucial in preventing or reducing insulin resistance, hyperglycemia, and type 2 diabetes." (PMID 38611884, 2024). "IFN-γ may also contribute to insulin resistance by reducing the expression of key proteins in the insulin signaling pathway, thereby promoting metabolic dysfunction in PCOS." (PMID 39691364, 2024). "It exhibits hypoglycemic actions, enhances insulin efficiency, and lessens insulin resistance." (PMID 38726403, 2024). "Low insulin sensitivity, or even insulin resistance, has been reported in both breeds." (PMID 39118059, 2024). "Administration of the CCB, metformin, or both together over 12 weeks significantly reduced glucose, insulin, and glycosylated hemoglobin (HbA1c) levels, as well as decreased insulin resistance (HOMA-IR) and increased pancreatic function (HOMA-B) in ZDF animals." (PMID 38257166, 2024). "Consequently, hyperinsulinemia arises as beta cells attempt to compensate for insulin resistance by increasing insulin secretion." (PMID 38397999, 2024). "Insulin resistance plays a key role in the pathogenesis of EP, and the identification of specific markers involved in insulin signaling and glucose metabolism could be useful for early detection and intervention." (PMID 38909214, 2024).
Insulin resistance (continued). "Additionally, there was a positive correlation found between inflammatory markers (hs-CRP, MCP-1, TNF-alpha, and PAI-1 levels), lipid profiles (LDL-c, TG, and TC levels), and insulin resistance (fasting glucose level, fasting insulin level, and HOMA-IR)." (PMID 38463431, 2024). "Further, the authors analyzed the insulin levels and insulin resistance in the two groups." (PMID 39216124, 2024). "Results suggest that SHP1 may be a potential target for muscle insulin resistance and insulin signaling during obesity, as well as the fact that it may be involved in the development of non-alcoholic fatty liver disease caused by diet-induced obesity." (PMID 38399444, 2024). "However, future trials examining the effect of RPS on GLP-1, insulin sensitivity, and fasting blood glucose in people with insulin resistance are warranted to confirm these effects." (PMID 39452917, 2024). "Additionally, patients with acromegaly are characterised by hyperinsulinemia and insulin resistance, and an appropriate sensitivity of the heart muscle to insulin is necessary to maintain the proper function of the circulatory system." (PMID 39598257, 2024). "It is still debated whether cancer cells remain insulin-sensitive or acquire insulin resistance to influence cancer progression." (PMID 39410536, 2024). "Interestingly, although fasting insulin and homeostasis model of insulin resistance (HOMA-IR) levels initially increased in both study arms, they returned to baseline after 6 weeks in the legume-enriched group." (PMID 38794673, 2024). "This may be due to AMPK activation in the muscle and liver improving insulin resistance, reducing insulin demand, and reducing the synthetic burden on β-cells." (PMID 38957396, 2024). "Kaempferol exhibits anti-diabetic effect in regulating hepatic gluconeogenesis and ameliorating fasting hyperglycemia and glucose intolerance through increasing AKT phosphorylation, oral administration of kaempferol improved insulin sensitivity and insulin resistance in HFD-fed mice." (PMID 38799166, 2024). "Furthermore, A. paniculata treatment significantly enhanced insulin sensitivity and reduced insulin resistance evident by a significant rise in HOMA-S, a reduction in HOMA-IR, an increase in QUICKI, and a reduction in TyG." (PMID 39545041, 2024). "Significant positive correlations were found between atherogenic index of plasma and age, lymphocyte, neutrophil, C-reactive protein, glucose, insulin, and homeostatic model assessment-insulin resistance, while the correlation with platelet/lymphocyte ratio was significantly negative." (PMID 39630767, 2024). "This uncertainty may stem from the distinction between the controlled therapeutic use of exogenous insulin and the endogenous overproduction observed in insulin resistance." (PMID 39595655, 2024). "Obesity often leads to insulin resistance, where the body’s response to insulin is diminished." (PMID 39560873, 2024). "Interestingly, the phosphodiesterase IV (PDE4D) inhibitor roflumilast has been reported to ameliorate the symptoms of T2DM and insulin resistance by potentiating cAMP signaling, possibly influencing insulin secretion." (PMID 39458839, 2024). "Based on these findings, it has been hypothesized that in the state of insulin resistance, the beneficial metabolic effects of insulin are converted to adverse effects." (PMID 39661465, 2024). "In addition, AITC and cinnamaldehyde interact directly with TRPA1 to improve insulin secretion and weaken insulin resistance, thereby showing anti-diabetic effects." (PMID 39273183, 2024). "Although H. pylori infection could not significantly affect serum inflammatory factor levels and serum biochemical parameters in mice, serum insulin and homeostatic model assessment for insulin resistance levels increased in CD mode." (PMID 39075482, 2024).
Insulin resistance (continued). "Specifically, we hypothesize that variations in iron metabolism markers correlate with different degrees of insulin sensitivity among the local population, including insulin-sensitive (IS) individuals and those with significant insulin resistance (SIR)." (PMID 39330480, 2024). "Ceramides are known to antagonize insulin action, thereby contributing to insulin resistance." (PMID 39290144, 2024). "Insulin resistance is triggered by overnutrition and physical inactivity, leading to pancreatic β-cell neogenesis and hypersecretion of insulin to compensate for the elevated insulin demand." (PMID 38297165, 2024). "Since insulin resistance plays a key role in NAFLD pathogenesis by increasing lipolysis in adipose tissue and delivering more free fatty acids to the liver, enhancing insulin sensitivity may significantly reduce NAFLD risk." (PMID 39723159, 2024). "Insulin resistance might disrupt insulin signaling, which would increase the concentration of THBS1 and worsen endothelial dysfunction and inflammation." (PMID 39050565, 2024). "Nonetheless, the acute stress might expose pre-existing latent issues such as insulin resistance, characterized by impaired pancreatic β-cell function, which affects insulin production." (PMID 39682557, 2024). "It has been reported that cytokines released from adipose tissue may be involved in initiating and promoting pro‐inflammatory states, and contribute to the regulation of insulin resistance and insulin sensitivity and secretion." (PMID 38577990, 2024). "Fasting blood glucose levels, serum fasting insulin levels, Homeostatic Model Assessment for Insulin Resistance (HOMA-IR), serum triglycerides, cholesterol, low-density lipoprotein-cholesterol, serum and urinary albumin, and creatinine and urea levels were measured." (PMID 38541120, 2024). "Due to an insufficient study base, we were also unable to conduct a meta-analysis of effects on insulin, C-peptide, and HOMA-IR; because of this, the impact of auricular pressure on insulin secretion and insulin resistance remains unclear." (PMID 39301316, 2024). "After the grip strength test was conducted, the animals were euthanized for blood and tissue collection to analyze glycated hemoglobin (HbA1c), plasma insulin, and insulin resistance using the homeostatic model of insulin resistance (HOMA-IR) index and malondialdehyde (MDA) concentration." (PMID 38612885, 2024). "Insulin resistance is defined as an abnormal glucose response to exogenous and endogenous insulin." (PMID 39768899, 2024). "However, even under insulin resistance states, the ability of 10− 6 M insulin to promote DPSC proliferation and osteogenic differentiation remained consistent over time." (PMID 39075596, 2024). "But BCAA dysmetabolism and as a consequence elevated BCAA levels and its metabolites can on the long-term have detrimental effect on insulin action and mitochondrial function facilitating the development of insulin resistance and an impaired glucose regulation." (PMID 39114126, 2024). "Furthermore, NEFA have shown to cause a rise in cytosolic Ca2+, favoring not only glucose-independent insulin secretion, but also potentiating glucose-stimulated insulin secretion in an attempt to compensate insulin resistance." (PMID 39456743, 2024). "In addition, the consumption of ginger has been shown to significantly reduce insulin resistance and improve insulin levels." (PMID 39021815, 2024). "The objective of this study ‎was to conduct a comparative analysis of blood glucose levels, hemoglobin A1c (HbA1c) levels, insulin hormone levels, and homeostasis model assessment of insulin resistance (HOMA-IR) ‎levels in diabetic patients who smoked and those who did not." (PMID 39478763, 2024). "However, the accumulation of MDSCs enhances insulin response, while the depletion of MDSCs results in reduced glucose tolerance and insulin resistance." (PMID 39518420, 2024).
Insulin resistance (continued). "Whether short SCD bouts at a self-selected pace improve insulin and insulin resistance, as well as PBG, after a mixed meal has yet to be examined." (PMID 38572086, 2024). "Also, we found that insulin and insulin resistance worsened in CHR during the one-year follow-up period." (PMID 39085221, 2024). "Insulin resistance selectively inhibits insulin’s glucose-lowering effects." (PMID 39021599, 2024). "In another double-blind, placebo-controlled, randomized trial involving healthy Japanese men over 40 years old, Chios mastic gum intake alone and in combination with physical activity led to significant reductions in insulin levels and insulin resistance compared to a control group." (PMID 38892571, 2024). "Under this infusion regimen, the ultimate resulting glucose level was interpreted as reflecting insulin resistance — clearly, if the resulting glucose level were high, one could conclude that insulin resistance was present." (PMID 38299589, 2024). "Therefore, promoting glucose uptake and insulin sensitivity in skeletal muscles plays a crucial role in preventing or reducing insulin resistance, hyperglycemia, and type 2 diabetes." (PMID 38611884, 2024). "From this set of data, it has been postulated that a shift toward a higher INSRα-A/B ratio may disrupt the canonical insulin signaling pathway, leading to peripheral insulin resistance." (PMID 37611907, 2024). "Furthermore, p21 has been identified as an inhibitor of insulin signaling and glucose uptake in adipocytes, thus contributing to insulin resistance." (PMID 39684919, 2024). "It has been hypothesized that obesity and insulin resistance may lead to a phenomenon similar to insulin or leptin resistance, known as FGF21 resistance, which is considered a self-protective mechanism of the body." (PMID 39409124, 2024). "In general, insulin resistance (IR) is defined as a decreased response of cells to insulin." (PMID 38392069, 2024). "This interleukin is also considered to be the initiator of insulin resistance because it has been shown that acute peripheral infusion of IL-6 may impair the action of insulin in mice." (PMID 38250713, 2024). "However, when insulin resistance occurs due to the impairment of insulin signaling, compensatory hyperinsulinemia develops as a result of excessive insulin secretion in the body." (PMID 39599757, 2024). "Increased ROS and inflammation may also worsen insulin resistance and impair insulin secretion in a reciprocal manner." (PMID 38892526, 2024). "Similarly, there was no significant change in other parameters like FBS, PPBS, fasting insulin, and insulin resistance (HOMA-IR)." (PMID 39463653, 2024). "In contrast, berberis primarily focuses on improving insulin sensitivity and reducing insulin resistance which may have a more substantial impact on long term markers such as HbA1c." (PMID 39413550, 2024). "In this study, we identify miR-6236 as the most abundant miRNA secreted by LAMs and show that miR-6236 counteracts the development of obesity-associated insulin resistance by inhibiting the translation of adipocyte PTEN, a well described negative regulator of the insulin signaling pathway." (PMID 38918428, 2024). "As an indication of insulin resistance, the fasting blood glucose and insulin concentrations and HOMA were measured which were noticeably elevated in groups III and VI than in groups I and II (p < 0.001).However; blood glucose and HOMA showed lower levels in group IV (p < 0.05)related to group III." (PMID 38316807, 2024). "Insulin resistance also develops, reducing the nerve-supporting effects of insulin." (PMID 39857603, 2024).
Insulin resistance (continued). "Salivaryleptin and insulin levels serve a purpose in monitoring insulin resistance and metabolic syndrome, while salivary cortisol is oftenemployed in endocrinology to assess adrenal function and aid in making diagnoses of Cushing's syndrome and Addison's disease." (PMID 40230914, 2024). "Conversely, higher scores on the Empirical Dietary Index for Hyperinsulinemia (EDIH) and the Empirical Dietary Insulin Resistance Index (EDIR) are associated with increased HCC risk, suggesting an interaction between diet and the insulin-related metabolic axis." (PMID 38992637, 2024). "Understanding the complex interplay between glutamine metabolism and insulin signaling may provide insights into the development of new therapies for insulin resistance and related metabolic disorders." (PMID 38255314, 2024). "This study showed that fructose/STZ administration to the diabetic group induced insulin resistance and type 2 diabetes, which were evident from their decreased serum insulin concentrations, elevated blood glucose levels, HOMA-IR, and HbA1C values compared to the control group." (PMID 39239455, 2024). "Additionally, FBS, hbA1C, insulin, Homeostatic Model Assessment for Insulin Resistance (HOMA-IR), total cholesterol, TGL, and LDL-C were also found to be statistically significant." (PMID 39350883, 2024). "Based on numerous studies, insulin resistance, obesity, and T2D have been shown to exhibit distinct alterations in the epigenome that result in the dysregulation of the key gene expression patterns involved in insulin signaling and/or lipid metabolism." (PMID 39595621, 2024). "This association may be explained by the fact that obese patients are more likely to experience poor glycemic control due to increased fat mass and visceral adiposity, which negatively impact insulin sensitivity and contribute to insulin resistance." (PMID 39633380, 2024). "It is now well known that zinc is involved in blood glucose homeostasis and is associated with insulin resistance, and insulin sensitivity through different mechanisms which are not fully understood and elucidated." (PMID 39596259, 2024). "With insulin resistance, increased insulin levels (hyperinsulinemia) are seen." (PMID 39518747, 2024). "Another investigation revealed that while exercise alone contributed to diminished insulin resistance and bolstered insulin sensitivity, a combination of diet and exercise substantially reduced insulin resistance, as indexed by HOMA–IR scores (MD, −1.99), with an average reduction of 2.07." (PMID 38248762, 2024). "Insulin resistance (IR) is a pathophysiological condition characterized by the diminished ability of insulin to exert its normal biological effects, particularly facilitating glucose entry into insulin-sensitive tissues to be used as the primary energy substrate." (PMID 39125938, 2024). "In type 1 DM, the pancreas does not produce insulin (mostly due to the immune system destroying islet cells), whereas in the much more common type 2 DM, there is less production of insulin, and the body develops insulin resistance, especially in people with obesity." (PMID 38256693, 2024). "Consequently, GH-induced insulin resistance can be attributed to a post-receptor defect in insulin action, leading to glucose intolerance and secondary hyperinsulinism." (PMID 39578883, 2024). "Moreover, O-GlcNAc is altered in the course of insulin resistance induced by glucosamine, identified as mammalian uncoordinated-18c (Munc18-c), a necessary protein aiding in the translocation of insulin-stimulated GLUT4." (PMID 39807459, 2024). "Additionally, exosomes from insulin-resistant adipocytes can exacerbate insulin resistance, promote vasa vasorum angiogenesis, and increase plaque burden and vulnerability in ApoE−/− diabetic mice." (PMID 39337658, 2024).